IL6 (interleukin 6)
Diseases named in the same sentence as IL6 in open-access papers (continued):
Sharing a sentence is not in itself a finding about the gene and the disease.
tumor (continued). "To identify whether PDT might create a milieu that would favour IL-6 trans-signalling, we employed a culture system of HeLa cells and primary human lung macrophages, representing the interacting components of tumour and inflammatory cells." (PMID 17987036, 2007). "Multivariate Cox analysis for overall survival, including IL-6 amplification, extent of tumour resection and age as variables, demonstrated that IL-6 amplification was an independent factor of poor prognosis (relative risk (RR) amplified vs non-amplified 8.07; P=0.000016)." (PMID 17224923, 2007). "Taken together, these data suggest that IL-6 trans-signalling can occur in the post-PDT tumour environment and that it may affect PDT-surviving tumour cells that have lost their IL-6Rα or cells that are inherently IL-6Rα negative." (PMID 17987036, 2007). "Interleukin-6 (IL-6) is known to promote tumour growth and survival." (PMID 17224923, 2007). "Given the fact that the in vivo tumour milieu contains copious amounts of IL-6 after PDT and macrophages are a component of the PDT-induced host cell infiltrate, these findings argue for a possible role of sIL-6Rα and IL-6/sIL-6Rα complex in PDT-treated tumours." (PMID 17987036, 2007). "IL-6 is a proinflammatory cytokine produced by inflammatory cells as well as tumor cells." (PMID 15847702, 2005). "A possible explanation may be that IL-6 has different roles in carcinogenesis according to the tumour type." (PMID 14735187, 2004). "In contrast, IL-6 was correlated with tumour burden independently of PSA." (PMID 15150588, 2004). "This involvement of IL-6 at a cellular level with the processes of cancer control is reflected by the results of serum studies of cancer patients, where IL-6 may reflect prognosis and tumour load." (PMID 15150588, 2004). "As tumours evolve toward a metastatic phenotype and interfere with other endogenous or exogenous factors, IL-6 activity on cancer cells and their environment might actually shift from growth inhibition and differentiation to proliferation and antiapoptosis." (PMID 12771987, 2003). "This suggests that, apart from the regulatory effects of IL-6 on VEGF production, other mechanisms are responsible for the deleterious effects of high serum IL-6 levels on tumour growth, thus explaining their strong correlation with prognosis in metastatic breast cancer patients." (PMID 12771987, 2003). "IL-6 might be a critical component of VEGF expression locally at the site of a growing tumour, but furthermore increasing the amount VEGF stored in platelets." (PMID 11875705, 2002). "We more specifically focused on the role IL-6 could have in both increasing the VEGF-content in platelets as well as in mediating fibrin formation in tumours." (PMID 12454774, 2002). "This suggests that tumour-produced IL-6 may induce fibrinogen expression in hepatic cells, herewith partly explaining the observed correlations between high ciculating IL-6 levels and circulating fibrinogen levels (P=0.005; r=0.69)." (PMID 12454774, 2002). "Thus, the environment where tumour cells grow would be a critical factor in determining the cachectic phenotype of cancer cells, including their ability to produce IL-6." (PMID 10070867, 1999). "The weight of tumours significantly correlated with the serum IL-6 level." (PMID 10070858, 1999). "The interaction of IL-6 with the angiogenic pathways in cancer might explain the stimulation of tumour growth occasionally observed during IL-6 administration." (PMID 10360671, 1999). "In contrast, only minute levels of IL-6 are detected in the tumour grown in the liver." (PMID 10070867, 1999). "IL-1alpha, and IL-6 enhanced tumour and normal cell growth by 20-120%." (PMID 9062407, 1997). "Indeed, it has been proposed that VNS may activate the cholinergic anti‐inflammatory reflex to suppress IL‐6‐driven tumor immune evasion, thereby sensitizing otherwise resistant gliomas to immune checkpoint inhibitors." (PMID 41583906, 2026).
tumor (continued). "For example, targeted depletion of M2 TAMs to restore CD8+T cell cytotoxicity in advanced OC; inhibiting the IL-6 pathway to attenuate STAT3-mediated tumor growth promotion; and modulating DCs migration to increase intratumoral distribution, which may enhance anti-tumor immunity." (PMID 41601649, 2026). "Similarly, IL-6 may enhance anti-tumor immunity by stimulating immune cell differentiation and activating acute-phase responses." (PMID 41497141, 2026). "A chimeric IL-6/IL-1β fusokine was engineered to test the hypothesis that enforced co-engagement of IL-6 and IL-1β signaling pathways would confer a gain-of-function phenotype in T cells and promote robust anti-tumor immunity." (PMID 42146708, 2026). "Future investigations should characterize macrophage subsets (such as iNOS/CD86 versus Arg1/CD206) using flow cytometry or multiplex immunostaining to determine whether macrophage-derived cytokines contribute to IL-6/STAT3 signaling during UVB-driven tumor promotion." (PMID 41596287, 2026). "As a pro-inflammatory factor, the level of cyr61 in ascites increases is associated with FIGO stage, initial tumor size > 10 cm, and residual tumor size, and may participate in the tumor metastasis and progression process by generating IL-6 and CRP in the OC inflammatory microenvironment." (PMID 41601649, 2026). "Additionally, copy number amplification of IL6 may upregulate the expression of pro-inflammatory factors, thereby promoting tumor progression and affecting the response to immunotherapy." (PMID 40257955, 2025). "In addition, MICs produce inflammatory mediators such as IL-1β, TNF-α, and IL-6, which may initially help initiate an anti-tumor immune response." (PMID 39897552, 2025). "Depending on their subtype, TAMs can produce either pro-inflammatory cytokines (e.g., IL-1β and IL-6) or anti-inflammatory cytokines (e.g., IL-4 and IL-10), thereby modulating the cytokine profile and shifting the tumor microenvironment toward either tumor suppression or tumor promotion." (PMID 40308575, 2025). "In addition, IL-6 can help tumor cells achieve immune escape through a variety of pathways." (PMID 41376630, 2025). "For example, TNF-α often promotes macrophages to polarize into the M1 phenotype, which has anti-tumor properties.Nonetheless, elevated levels of IL-6 might prevent M1 macrophages from polarizing and encourage their transformation into the M2 phenotype, which supports tumor growth." (PMID 40242775, 2025). "Therefore, IL-6 in the tumor microenvironment may affect the efficacy of tumor immunotherapy by affecting anti-tumor immunity." (PMID 40433391, 2025). "Over 90% of CCAs are surrounded by a dense desmoplastic tumor environment comprising cancer-associated fibroblasts and macrophages, which express high levels of IL-6, and recent studies suggest that CCA tumor growth is stimulated by autocrine IL-6-mediated signaling." (PMID 40419900, 2025). "Additionally, AEF treatment reduced interleukin 6 (IL‐6) levels, a characteristic feature of the tumour microenvironment that promotes tumorigenesis by regulating various cancer hallmarks and multiple signalling pathways, including proliferation, apoptosis, angiogenesis and metastasis." (PMID 39161078, 2025). "Under the influence of TGF-β, IL-8, IL-6, and IL-17, neutrophils polarize into the N2 subtype, characterized by prolonged lifespan, an immature phenotype, reduced cytotoxicity, and pro-tumor functions, including promotion of tumor growth, invasion, metastasis, angiogenesis, and immune suppression." (PMID 40948800, 2025). "After treatment with quadrigemine I (1.25 and 5 mg/kg), the inhibition rates for IL-6 were 20.95 ± 0.30% and 30.00 ± 0.86% in serum, 2.13 ± 1.99% and 22.91 ± 0.71% in liver tissue, 5.10 ± 0.62% and 25.33 ± 0.98% in spleen tissue, and 2.74 ± 0.40% and 14.17 ± 0.09% in tumor tissue." (PMID 40429988, 2025).
tumor (continued). "The results showed that compared to cGAMP, XA5508 could significantly increase the expression levels of immune factors IFN-β, IFN-γ, IL-2, IL-6, and TNFα in the mice, and significantly reduce the expression of the immunosuppressive tumor-promoting factor IL-10." (PMID 40943568, 2025). "It has been found that serum IL-6 shows an elevated level in a variety of malignant tumors, which may play a role in the development of tumors by affecting the survival, proliferation, and angiogenesis of tumor cells." (PMID 40919145, 2025). "Furthermore, 1,25(OH)2D suppresses the activation of proinflammatory factors, such as IL‐1 and IL‐6, suggesting that Vitamin D itself may possess potential anti‐tumor effects." (PMID 40922928, 2025). "Therefore, we could state IL-6 and its pleiotropic role positively drives the physiology of growing tumor cells towards achieving chronic states in NSCLC." (PMID 41376623, 2025). "Besides, serum TNF-α and IL-6 levels were reduced after Z526 treatment in C26 tumor-bearing mice." (PMID 39759112, 2025). "Importantly, the combination therapy enhanced CD4+ and CD8+ T-cell infiltration, increased the production of pro-inflammatory cytokines such as IL-2, and reduced the expression of immunosuppressive factors such as IL-6, indicating an immunomodulatory effect that improved anti-tumor immunity." (PMID 41041327, 2025). "Functional analyses confirmed that TG7 promotes tumor cell proliferation, and that its silencing using DsiRNA3 led to a dose-dependent reduction in cell viability, accompanied by the upregulation of pro-inflammatory cytokines IL6 and TNFα, as well as the apoptotic marker CASP3." (PMID 41425727, 2025). "Meanwhile, in the TME, tumor-associated fibroblasts and immunosuppressive cells, including myeloid-derived suppressor cells (MDSCs), regulatory T cells (Tregs), and M2-type tumor-associated macrophages (TAMs), release signaling substances such as TGF-β and IL-6 that promote drug resistance." (PMID 40948763, 2025). "This pattern may reflect a dysregulated mucosal immune response in which F. nucleatum disrupts the normal balance to promote a tumor-supportive chronic inflammatory state (IL-17–dominant), while bypassing the IL-6–driven acute immune response that might otherwise trigger stronger cytotoxic activity." (PMID 41267807, 2025). "These tumor-associated MSCs differentiate into cancer-associated fibroblasts (CAFs), which secrete pro-angiogenic and immunosuppressive factors, including PDGF, FGF, VEGF, IL-6, and IL-8, that promote cancer cell survival, angiogenesis, immunosuppression, tumor growth, and metastasis." (PMID 41169880, 2025). "Additionally, the upregulation of IL6 may indicate an immune-mediated tumor suppression effect, warranting further investigation." (PMID 40746726, 2025). "Furthermore, combining IL6 levels with miRNA21 expression levels may aid in predicting tumor progression and chemoresistance." (PMID 40427188, 2025). "Furthermore, a correlation with a worse prognosis has been observed, which may be attributable to the inhibition of the anti-tumor response by IL-6." (PMID 41007818, 2025). "While IL6 is traditionally considered pro-tumorigenic, its elevation in this study may reflect immune activation, possibly enhancing myeloid cell-mediated tumor surveillance or counteracting T-cell exhaustion, as indicated by scRNA-seq localization of IL6 in myeloid compartments." (PMID 40746726, 2025). "Similarly, a reduction in tumor growth in the B16-OVA tumor model was observed only when adoptive cell transfer of OT-1 effector T cells was combined with the administration of recombinant IL-6." (PMID 39653766, 2025). "Therefore, IL-6 inhibition is considered a possible tumor therapeutic strategy." (PMID 40699630, 2025). "Moreover, some studies suggest that IL-6 expression may decrease in advanced-stage tumors, potentially reflecting adaptive changes in the tumor microenvironment." (PMID 41007818, 2025).
tumor (continued). "Moreover, GP130 pathway inhibition may convey potent anti-tumor effects, so we examined PreAdip cells as a possible source of IL6 and its impacts on DDLPS oncogenic behaviors via GP130 signaling." (PMID 40961077, 2025). "However, the prolonged suppression of key cytokines such as IL-6 and IL-8 could compromise immune function and tissue repair capacity and may even increase vulnerability to tumor development due to impaired immune surveillance." (PMID 40277933, 2025). "Studies have shown that prolonged treatment with IL-6 receptor (IL-6R) antibodies can block IL-6 signaling and reduce muscle atrophy in tumor-bearing mice, suggesting that anti-IL-6 receptor antibodies could have therapeutic potential in addressing cancer-associated muscle wasting." (PMID 40104495, 2025). "In combination, the tumor-promoting pro-inflammatory activity as well as the immunosuppressive activity may represent crucial molecular processes underlying the potent oncogenicity of combined HH/GLI and IL6/STAT3 signaling." (PMID 39962447, 2025). "Compared with previous studies, the current research confirmed the association between baseline IL-6 and advanced ESCC patient prognosis and revealed IL-6’s close relationship with tumor immune cell expression and the immunosuppressive molecule PD-L1 within the tumor microenvironment." (PMID 40433391, 2025). "Furthermore, we previously identified tumor-secreted factors such as tumor necrosis factor-alpha (TNF-α) and IL-6 as candidate ototoxic molecules that could be associated with hearing loss in VS patients." (PMID 39923035, 2025). "However, the strength of IL-6 signals in CD4+ T cells versus tumor cells could differ, and targeting IL-6 to inhibit GBM tumor growth may need to consider its impact on CD4+ T cells, which needs to be further explored." (PMID 39885128, 2025). "MDSCs have an oncogenic role in TME, as they promote tumor growth and progression by mediating neoangiogenesis (secretion of MMPs, VEGF, and cytokines implicated in angiogenesis) and epithelial–mesenchymal transition (EMT) (secretion of IL-6, TGF-β, and S100A8/A9)." (PMID 41369383, 2025). "Also, CPMV could induce the release of pro-inflammatory cytokine IL-6, enhance the antigen-processing capacity of APCs, and initiate the activation of tumor-specific cytotoxic T cells in the tumor microenvironment." (PMID 40333256, 2025). "In addition, IL-6 can also inhibit the maturation and antigen presentation function of dendritic cells, further reducing the immune system’s ability to respond to pathogens or tumor cells." (PMID 41376630, 2025). "This further suggests that IL-6 plays a critical role as a pro-inflammatory cytokine in the tumour microenvironment and its elevated levels in CC patients may reflect ongoing chronic inflammation, which promotes tumour growth, angiogenesis and immune evasion." (PMID 41561529, 2025). "Furthermore, preliminary findings suggest that EBF1 may regulate interleukin-6 (IL-6) expression, thereby modulating multiple IL-6-related downstream pathways involved in tumor progression." (PMID 40508012, 2025). "Indeed, given the previously proposed decoupled effect of IL-6 blockade in enhancing both anti-tumor and anti-inflammatory responses, several clinical trials have been initiated in recent years to evaluate the efficacy and safety of IL-6-targeting therapies in patients undergoing ICI treatment." (PMID 41019062, 2025). "To determine whether mammalian lipases functionally homologous to CG5966 act downstream of IL-6 in tumor-bearing mice, we profiled the expression of its putative orthologs (Pnlip and Lpl) in the liver as well as adipose tissue, the major TG storage site in mammals." (PMID 41256541, 2025). "Furthermore, CAFs may alter the anti‐tumor immune response through secretion of several immune modulators such as IL6, CCL2, CXCL12, and TGFβ2, which we found to be up‐regulated in CMS4 PM." (PMID 39739693, 2025).
tumor (continued). "Additionally, we observed higher expression levels of pro-inflammatory cytokines, including IL-6 and TNF-α in high-risk samples, which may reflect an inflammatory state within the tumor microenvironment." (PMID 40601653, 2025). "The tumor microenvironment comprises various stromal and immune cells, including cancer-associated fibroblasts, M2-polarized macrophages, regulatory T cells, endothelial cells, and mesenchymal stem cells, which secrete critical factors such as TGF-β, TNF-α, IL-6, and VEGF." (PMID 41013839, 2025). "To investigate whether HIF1α, a principal transcription factor activated under hypoxic conditions within the tumor microenvironment, contributes to the regulation of IL-6 production, we employed siRNA-mediated knockdown of HIF1α in PC-9 cells followed by exposure to hypoxia." (PMID 41254082, 2025). "This marked elevation suggests that while gefitinib effectively targets EGFR signaling, it may concurrently activate compensatory or stress-related pathways that drive IL-6 production—a cytokine known to support tumor growth, immune evasion, and therapeutic resistance." (PMID 41401147, 2025). "Therefore, reduced m6A levels in tumour‐derived EVs may promote CRC recurrence by enhancing IL‐6 and TNF‐α production by macrophages within the tumour." (PMID 40326665, 2025). "We speculate that in the context of active immunotherapy-driven tumor destruction, blocking IL-6 signaling might compromise the potential therapeutic advantages associated with high baseline TGFβ-specific immunity in patients with PDAC receiving immune checkpoint inhibition and radiotherapy." (PMID 39653766, 2025). "Elevated IL-6 levels were strongly associated with advanced stages of HCC, reflecting heightened inflammation and liver damage, while higher IL-10 levels were observed in early tumor stages, indicating a role in early carcinogenesis and tumor-induced immunosuppression." (PMID 41379186, 2025). "Furthermore, it has been shown that IL-6 protects tumor cells from therapy-induced DNA damage." (PMID 40649953, 2025). "However, other mechanisms may also be involved such as the inflammatory response to surgery which is frequently accompanied by increases in immunosuppressive cytokines such as TGF-b, IL-6, and GM-CSF which may dampen anti-tumor responses." (PMID 41209004, 2025). "Therefore, we investigated whether the effects of MCPIP1 on tumor EMT and tumor stemness were mediated by targeting the IL6/JAK2/STAT3 signaling pathway." (PMID 40874680, 2025). "Furthermore, IL‐6 contributes to tumor progression by promoting angiogenesis, tumor infiltration, and immune suppression, creating a favorable environment for tumor growth." (PMID 41316520, 2025). "In addition, elevated TNF-α and IL-6 levels in the serum of C26 tumor-bearing mice were observed, which could be down-regulated to near-normal levels by Z526." (PMID 39759112, 2025). "Elevated levels of certain cytokines, such as IL-6, IL-17, and IL-8, have been linked to tumor progression, whereas others, including IL-1, TNF-α, TGF-β, and IFN-α, play a role in suppressing HPV replication and tumor growth, especially during the early stages." (PMID 40142865, 2025). "Therefore, overexpression of IL-6 in the tumor tissues may contribute to immunosuppression within the tumor microenvironment of ESCC patients." (PMID 40433391, 2025). "Additionally, elevated levels of IL-6 are strongly related to the growth, differentiation, and immigration of tumor cells, as well as with resistance to chemotherapy and radiotherapy, rendering IL-6 one of the most important cytokines in the tumor microenvironment." (PMID 40731649, 2025). "TAMs are actively recruited and conditioned by the tumor: cancer cells and stromal cells, like cancer-associated fibroblasts, secrete CCL2 and colony stimulating factors that recruit monocytes and induce their differentiation into MDSCs and M2 TAMs via STAT3-activating cytokines (IL-6, etc.)." (PMID 40227782, 2025).